CTLA4 (cytotoxic T-lymphocyte associated protein 4)
Diseases named in the same sentence as CTLA4 in open-access papers (continued):
Sharing a sentence is not in itself a finding about the gene and the disease.
tumor (continued). "Strikingly, single-dose AIPV administered to animals bearing large ~40–50 mm2 tumors followed by PD-1 and CTLA-4 blockade (hereafter, ICB) led to tumor regressions comparable with the “full” AIPV regimen, with complete responses in 80% of animals." (PMID 34818534, 2021). "Several pre-clinical trials evaluated the effects of CTLA-4 inhibition in GBM mouse models, showing differences in the outcomes depending on the tumor model evaluated." (PMID 34168976, 2021). "Both CD4_5 and CD4_7 had expression of regulatory T (Tregs) cell markers, with higher levels of FOXP3, IL2RA (CD25), CTLA4, and TNFRSF18 (GITR) in the tumor-predominant CD4_5." (PMID 33504936, 2021). "The addition of immune checkpoint blockade, especially of anti-CTLA-4, greatly improves PLGA-MP-mediated cancer immunotherapy by a reinvigoration of antitumor immunity after cessation of microparticle-induced tumor-specific CTL response." (PMID 34006895, 2021). "Further, activated CAR-T cells mainly express immune checkpoint molecules, including CTLA4, PD1, LAG3, abrogating CAR-T anti-tumor activity." (PMID 34321099, 2021). "Tumor response to anti-PD1 and anti-CTLA4 therapies was predicted using TIDE and further validated using SubMap." (PMID 35111196, 2021). "CTLA-4 blockade alone resulted in 80% of long survivors and abrogated Treg expansion in SMA-560 tumor-bearing mice." (PMID 34168976, 2021). "The univariate and multivariate analyses revealed that CTLA4, HAVCR2, age, pTNM stage, and tumor grade were independent factors affecting the prognosis of KIRC patients." (PMID 34336706, 2021). "In patients, both anti-CTLA4 therapy and anti-PD1 therapy similarly increased T cell clonality in the tumor, but the extent of clonal expansion in the tumor pre-treatment was only predictive of outcome following anti-PD1 therapy." (PMID 33968757, 2021). "Next, we investigated if UPS tumours were sensitive to both anti-PD1 and anti-CTLA-4 immune checkpoint blockade." (PMID 34242269, 2021). "Like the role of immune checkpoint receptors PD-1 and CTLA-4 play in suppressing effector T cell functions, the CD47-SIRPα signaling axis inhibits the antibody-dependent phagocytosis of tumor cells by macrophages." (PMID 34771482, 2021). "Most mice that received only local treatment to the primary tumor spontaneously developed lung metastases, but when combined with BEMPEG and anti-CTLA-4, this was significantly reduced (p<0.05)." (PMID 33937052, 2021). "Allison discovered that the blockade of CTLA-4 with monoclonal antibodies restricted the binding of CTLA-4 to its ligands and increased anti-tumor immune responses with tumor rejection." (PMID 33925389, 2021). "GSEA of Biocarta pathways identified five up-regulated pathways with FDR < 0.05 in the M3 iSubtype, which were mainly involved in immune system (CTLA4, CSK, TCR) and tumor progression (SPPA, BAD)." (PMID 34944787, 2021). "In order to target non-redundant immune regulatory pathways, such as those activated by TGFβ and PD-1/PD-L1 or CTLA-4 expression, we proposed combining ICB with isoform-specific TGFβ inhibition in order to improve CD8+ T cell responses and anti-tumor immunity." (PMID 34789823, 2021). "Like CTLA4 the chemokine receptor type 4 (CCR4), albeit being expressed on peripheral Tregs, is further upregulated on tumor-infiltrating Tregs, while additionally being expressed on different types of cancer cells." (PMID 33679808, 2021). "PD1, TIM3, LAG3, and CTLA4, expressed on the surface of CD4+ and CD8+ T cells, indicate the occurrence of tumor immune escape phenomenon in PVNS pathogenesis." (PMID 34248943, 2021). "First, using specific sensitive ELISA, we validated that IL-6 plasma levels are elevated in tumor-free mice treated with anti-PD1 and anti-CTLA-4 antibodies." (PMID 33707313, 2021).
tumor (continued). "This co-dependency benefits the tumor, but it also implies that therapies that target one population may also reduce the immunosuppressive activity of the other cell population (i.e., the application of anti-PD-L1 or anti-CTLA-4 inhibitors in the clinical setting)." (PMID 33430105, 2021). "The frequency of eTreg cells decreased with the use of anti-CTLA-4, along with a decrease in the expression of CTLA-4 in eTreg cells and a reduced tumor growth." (PMID 33692219, 2021). "This activates the adenosine receptor A2aR on tumour cells and CD8+ T-cells which subsequently upregulates their PD-1 and CTLA-4 expression." (PMID 34944851, 2021). "The KN406 antibody is protected by ZIF‐8 in normal tissue but released in tumors to block the binding of PD‐L1 to PD‐1 and CTLA‐4 to CD80/CD86, thereby effectively enhancing the killing of tumor cells." (PMID 34473430, 2021). "After CTLA4-targeted NIR-PIT, activation and infiltration of CD8+ T cells was observed in the treated tumour beds." (PMID 34332294, 2021). "Collectively, these preclinical findings suggest that in the setting of CTLA4 blockade, radiation therapy broadens the TCR repertoire, an essential step to generating effective immune responses for tumor rejection." (PMID 34733273, 2021). "In support, circadian signals hold promise as anti-CTLA-4 therapeutic complements given their role in an alternative immune pathway that induces TH17 differentiation and activation, thus boosting host anti-tumor immunity." (PMID 33794967, 2021). "In terms of LUAD patients, most biomarkers, including IDO1, CTLA4, LAG3, CD40, TNFRSF18, TIGIT, and TNFSF14, were significantly increased in tumor tissues with high B cell abundance compared with that of low B cell group." (PMID 34422829, 2021). "Based on this approach, a novel recombinant humanized PD‐L1/CTLA‐4 bispecific single‐domain antibody‐Fc fusion protein (KN046) was designed to bind to both PD‐L1 and CTLA‐4 and effectively enhance the killing of tumor cells." (PMID 34473430, 2021). "Interactions between CTLA-4 and its ligands, CD80 and CD86, inhibit T cell activity and consequently induce tumor progression." (PMID 34298809, 2021). "In B cells, engagement of CTLA-4 with CD86 induced STAT3 activation through TIK2, increasing B cell lymphoma proliferation and tumor proliferation." (PMID 34572799, 2021). "Then, the Tumor Immune Dysfunction and Exclusion (TIDE) algorithm and SubMap were applied to predict the clinical response to immune checkpoint blockade (CTLA-4, PD-1, and PD-L1) in different subgroups." (PMID 35071242, 2021). "Tumor-infiltrating NK cells’ function can also be dampened by NK cell-autonomous inhibitory checkpoints such as PD-1, TIGIT, CD96, TIM-3, LAG-3, CTLA-4, KIR2DL-1/2/3 and NKG2A." (PMID 34692696, 2021). "A combination of anti-CTLA4 and TIM-3 blockade was found to shrink the tumor in preclinical studies." (PMID 34777336, 2021). "It has been suggested that overexpression of immunosuppressive molecules (e.g., CTLA4, LAG3, and PD1) and immunosuppressive cells (e.g., Tregs) are involved in tumor immune escape and contribute to tumorigenesis and progression." (PMID 34490047, 2021). "The primary tumor responded to PD1, OX40, and PD1+CTLA4 treatment with increased production of IFNg, and accompanying increases in the IFN-regulated chemokine IP-10 (CXCL10) and the proinflammatory chemokine RANTES (not shown)." (PMID 34221953, 2021). "It is also well-established that upregulation of two critical inhibitory receptors of CTL, namely PD-1 and CTLA-4, leads to CTL exhaustion and thereby tumor progression." (PMID 34952595, 2021). "In addition, multivariate analysis that included the number of tumor-associated non-synonymous mutations, predicted neo-antigen load and PD-L2 expression was capable of further stratifying responders and non-responders to anti-CTLA4 therapy." (PMID 33547395, 2021).
tumor (continued). "Tumor cells produce soluble molecules, such as IDO, PEG2, TGF-β, and a series of membrane molecules, including PD1, PD-L1, LAG3, TIGIT, and CTLA4." (PMID 34177887, 2021). "The recent discovery of immune checkpoint molecules (PD-1, PD-L1, CTLA-4, TIM-3, etc.)in the biology of tumor immune evasion has revolutionized the world of oncology." (PMID 35103180, 2021). "T-cell expression of CTLA-4 is elevated by TGF-β, a suppressive cytokine secreted by the tumor cells." (PMID 34790566, 2021). "Among the immunotherapies tested, IFNα was more effective than anti-PD-L1, anti-CTLA-4, anti-4-1BB, IL-2, and IL-9 in reducing Myc-CaP CRPC tumor growth." (PMID 34771735, 2021). "TOX promotes cell exhaustion in tumor-infiltrating CD8+ T cells by expressing IC molecules, such as PD-1, TIM-3, TIGIT, and CTLA-4." (PMID 34895349, 2021). "Once average tumor size reached ~80 mm3, mice were randomized and treated with combinations of three fractions of 8 Gy RT, BEMPEG, and/or anti-CTLA-4." (PMID 33937052, 2021). "CSF1R inhibition by PLX3397 reduces TAMs' tumor infiltration and their immunosuppressive phenotypes, potentiates ICI effects against PD-1 and CTLA4, and impairs tumor expansion by approximately 50%." (PMID 34476174, 2021). "Interestingly, immunohistochemistry of paraffin-embedded tumor blocks from perihilar and distal CCA patients who underwent surgery demonstrated that high levels of CTLA-4 on TILs were associated with prolonged overall survival, suggesting that CTLA-4 may have prognostic value." (PMID 34440865, 2021). "All these immune cells can express other co-inhibitors such as TIM-3, CTLA-4 and TIGHT to mediate tumor immune resistance." (PMID 34680282, 2021). "The NK cells were directly stimulated by the anti-CTLA-4/anti-PD-1 mAbs to produce IFN-γ, thereby contributing to senescence induction in tumor cells." (PMID 33141285, 2021). "These mAbs, upon binding to CTLA4 present on tumor-infiltrating Treg cells, induced ADCC activity, thereby resulting in tumor-infiltrating Treg cells depletion and enhanced tumor regression." (PMID 33391547, 2021). "The exact mode of action of anti-CTLA-4 ICB and the role of tumor cell-intrinsic CTLA-4 expression with regard to responsiveness to ICB is still only poorly understood." (PMID 33196890, 2021). "Treg depletion enhanced vaccine-mediated anti-tumor immunity in patients with metastatic RCC and dual CTLA-4 blockade and CD25+ Treg depletion maximized tumor rejection." (PMID 34503058, 2021). "Forkhead box protein P3 (FoxP3)-positive Tregs highly express OX40, CTLA-4 and CD25 and can be depleted to achieve stronger anti-tumor effects in combinatorial strategies." (PMID 33466732, 2021). "Strong synergistic effects were demonstrated in mouse tumor models for the combination of NKTR-214 and an anti-CTLA-4 monoclonal antibody." (PMID 33804800, 2021). "We further compared SB28 tumors grown intracerebrally versus subcutaneously to determine how tumor site affects TIME and responsiveness to dual CTLA-4/PD-1 blockade." (PMID 34083417, 2021). "Some of these signature genes (e.g., CTLA4, GITR, CCR4) are likewise present on peripheral Tregs, whereas their expression is increased in tumor-infiltrating Tregs." (PMID 33679808, 2021). "Relative to other tumor-infiltrating T cells, CD103+ TRM also displayed upregulation of immune checkpoint receptors such as PD-1, LAG-3, CTLA-4 and TIM-3." (PMID 34571883, 2021). "Here, we focused on the immunological reaction of tumor infiltrating lymphocytes, as the TME regulate immune-checkpoint proteins, such as PD-1, CTLA-4, Tim-3, and Lag-3." (PMID 34564709, 2021). "The levels of tumor-infiltrating Tregs were significantly decreased and the CD8:Treg ratio significantly increased by GPB730 treatment in combination with anti-CTLA-4 compared to anti-CTLA-4 alone." (PMID 33786638, 2021).
tumor (continued). "The efficacy of anti-CTLA-4, anti-PD-1, and anti-PD-L1 therapies is correlative to the levels of expression of CTLA-4, CD80/86, PD-1, and PD-L1 in the patients’ tumor cells, APCs, and T cells." (PMID 34136405, 2021). "By binding to CTLA-4 on the surface of the effector lymphocytes, Nb36 was able to increase the activation of DC-CIK cells, with stronger cytotoxicity and anti-tumor effects." (PMID 34525966, 2021). "In the NSCLC tumor microenvironment, several mechanisms for immunosuppression may operate in concert as a combination of immunotherapy targeting both the PD-1/PD-L1 axis and cytotoxic T lymphocyte protein 4 (CTLA-4) in cancer patients has given promising results." (PMID 33918618, 2021). "By targeting both receptors in a bispecific manner, the activity of the bsAb is not only directed to the tumor side, eventually introducing anti-tumor responses, but also may result in a more favorable safety profile and better efficacy compared to standard anti-CTLA4 mAbs." (PMID 34123841, 2021). "We analyzed the expression of immune checkpoint (IC) molecules (IDO, TIM-3, LAG-3, CTLA-4 (CD152), PD-1, PD-L1, PD-L2, B7-H3, B7-H4, B7-H5, and TIGIT) to provide a theoretical basis for tumor immunotherapy." (PMID 34660294, 2021). "TIM-3, CTLA4, and TIGIT primarily trigger peripheral tolerance and promote tumor growth by inhibiting the activity of effector T cells." (PMID 33575321, 2021). "Immunization with VEEV-TRP-2 and anti-GITR mAbs induced complete tumor regression in 90% of mice, whereas VEEV-TRP-2 and anti-CTLA-4 treatment resulted in tumor shrinkage in 50% of animals." (PMID 34696295, 2021). "The majority of tumors thrive in their host environment by neutralizing anti-tumor immunoregulatory signals, such as PD1/PDL1 and CTLA4, that block the cytotoxicity of immune cells and result in immunotherapy failure." (PMID 34068491, 2021). "Seminal discoveries made by Allison and Honjo provided preclinical proof of concept data that blockage of CTLA4 and PD1 signaling unleashes marked anti-tumor immune responses." (PMID 34853305, 2021). "Upregulation of checkpoints (PD-1, CTLA-4, and TIM-3) and their ligands (PD-L1 and PD-L2) in the TME can mediate tumor cells to escape immune surveillance by modulating T-cell activity." (PMID 34745101, 2021). "These Treg cells in Cd300afl/fl;ItgaxCre mice showed higher expression of Ki67 and CTLA-4 than did Cd300afl/fl mice, although the expressions of CD25, GITR, and BCL2 on tumor-infiltrating Treg cells were comparable between two genotypes of mice." (PMID 34751648, 2021). "In patients with NSCLC PD-1, TIM-3, CTLA-4, LAG-3, and BTLA inhibitory receptors were detected on TILs with a gradual and continuous upregulation during tumor progression, in 24 tumor lesions." (PMID 35069581, 2021). "Compared with circulation or lymph nodes, tumor-infiltrating FoxP3high effector Tregs are highly activated and express high levels of activation molecules including CD25, ICOS, PD-1, CTLA-4, OX40, GITR and TIGIT." (PMID 33532902, 2021). "Inspired by the combination of anti-PD-1 and anti-CTLA4 in lung cancer, the combination of different checkpoint inhibitors (anti-PD-1, anti-NKG2A and anti-TIGIT) was investigated and synergistic anti-tumor effect was observed in preclinical experiments." (PMID 33262461, 2021). "Whereas CTLA4 signaling occurs in the tumor-draining lymph nodes, PD1/PDL1 blockade occurs at the tissue level and in the tumor microenvironment." (PMID 34208848, 2021). "We found that the exhausted CD8+ T cells located in the core of the tumor had a higher expression of immune checkpoint molecules, including PDCD1, CTLA4, LAG3, TNFRSF9/CD137, CD27, and HAVCR2." (PMID 34513820, 2021). "Anti-CTLA-4 mAbs were initially thought to suppress the inhibition on activated CD4+ and CD8+ T cells and augment the anti-tumor immune response in the TME." (PMID 34806028, 2021).
tumor (continued). "Over the past few decades, immunotherapy has shown remarkable efficacy in the treatment of cancer, particularly the success of immune checkpoint blockade targeting CTLA-4, PD-1 and PDL1, which has led to a breakthrough in tumor immunotherapy." (PMID 33936118, 2021). "Eight tumor-related immunosuppressive molecules, CD274, CTLA4, HAVCR2, LAG3, PDCD1 (PD1), PDCD1LG2, SIGLEC15, and TIGIT, had higher expression in HNSCC tumor tissues compared with HNSCC normal tissues." (PMID 34917682, 2021). "In naive/Tcm CD4 T cells, there was reduced expression of CD28, ICOS, and OX40 in tumor compared with normal, with little PD1 expression and reduced CTLA4 expression in tumor T cells." (PMID 34936871, 2021). "E0771 tumor-bearing fat pad-infiltrating CD4 and CD8 T cells expressed elevated CD69, PD1, CTLA4, and CD25; with increased Tregs expressing inhibitory receptors PD1 and CTLA4." (PMID 33767151, 2021). "These mice had increased mononuclear cell infiltration in the liver, colon, lung, and pancreas after treatment with both anti-PD-1 and anti-CTLA-4 antibodies and following MC38 tumor challenge." (PMID 33571254, 2021). "The two hypomethylated hub genes, CTLA4 and CDSN, were significantly upregulated, and two hypermethylated hub genes, ACTN2 and MYH11, were downregulated in the HNSC tumor samples." (PMID 35096593, 2021). "Tumor neoantigen-specific SPAS-1+ T cells were significantly increased in each organ following dual therapy, when compared to anti-CTLA-4 monotherapy treatment." (PMID 34162858, 2021). "The production of IFN-γ by tumor-reactive CD8+ T cells was enhanced and the number of splenic Treg cells was decreased in mice treated with both CTLA-4 and belinostat combination." (PMID 34262562, 2021). "CTLA4-CAR T cells exhibited superior cytokine secreting activities and cytotoxic to tumor cells in vitro and in xenograft models." (PMID 33868277, 2021). "Other markers of activation/exhaustion were also elevated on tumor-infiltrating T cells after mRIPO (CD69, CTLA4, PD1, TIM3)." (PMID 33767151, 2021). "In our study, ipilimumab, an anti-CTLA4 antibody that binds to CTLA4 specifically, showed the anti-GBM efficacy in inhibiting tumor growth via at least partly preserving T cells in the HPDOX model." (PMID 34178691, 2021). "Compared with ipilimumab (a type of anti-CTLA-4 antibody) monotherapy, the anti-CTLA4-TGF-βR2 molecule presents more effective at decreasing tumor-infiltrating Treg cells and suppressing tumor progression." (PMID 34635121, 2021). "Known ligands of CTLA-4 are CD80 and CD86, while PD-1 binds to its coreceptors PDL-1/2, expressed also by cancer cells, to impair anti-tumor T-cell responses." (PMID 34771694, 2021). "Tumor progression was monitored following treatment with vehicle, the small molecule STAT3 inhibitor GPB730, anti-CTLA-4 or GPB730 + anti-CTLA-4." (PMID 33786638, 2021). "A study shows that anti-CTLA4 immunoglobulin G (IgG)-loaded MSN delivers the mAb against immunoregulatory molecule CTLA4, which modifies the host response to the tumor leading to antitumor activity." (PMID 33503889, 2021). "More importantly, the efficiency of ADH-1 in decreasing the tumor size and prolonging mouse survival time was better than those of anti-PD-1, anti-IDO-1 and anti-CTLA-4 when used individually or in combination." (PMID 33692219, 2021). "CTLA-4 has been shown to be indispensable in Treg-mediated immunosuppression, as CTLA-4− Treg cells were unable to maintain self-tolerance and immune homeostasis, and Treg-specific CTLA-4 deactivation promoted anti-tumor immunity." (PMID 33923750, 2021). "While anti-CTLA-4 eliminates the inhibition of CD4+ T cell activity in the lymph nodes, anti-PD-L1 is directed against the blockage of the CD8+ T cells in the tumor and in the peritumoral tissue." (PMID 33921668, 2021).